SLC7A11 (solute carrier family 7 member 11)
Diseases named in the same sentence as SLC7A11 in open-access papers (continued):
Sharing a sentence is not in itself a finding about the gene and the disease.
breast cancer (continued). "Moreover, analysis of 59 breast cancer cells showed a marked and selective negative correlation between the expression of SLC7A11 and mitochondrial OXPHOS genes." (PMID 28429737, 2017). "Importantly, differential changes in SLC7A11 (xCT) mRNA levels were validated by RNA-sequencing, further confirming that STAT3/5 signaling is central to the transcriptional regulation of xCT in human breast cancer cells." (PMID 27513743, 2016). "Moreover, overexpression of miR-27a in breast cancer cells not only attenuates mammosphere formation and survival but also chemosensitizes breast cancer cells by down-regulating glutathione-related NRF2, CTH, and SLC7A11, leading to attenuation of ROS defense system and autophagy." (PMID 40028033, 2025). "To explore ferroptosis features in NAT10-depleted breast cancer cells, we performed a cystine uptake assay and observed a remarkable decrease in cystine levels in NAT10-depleted cancer cells, suggesting that cystine uptake could be impaired due to downregulation of SLC7A11 mRNA." (PMID 37237981, 2023). "In recent studies, researchers reported that SSZ, an inhibitor of SLC7A11, could induce cysteine/cysteine starvation, leading to GSH depletion, which may be useful for therapy against many cancers such as lymphoma, prostate cancer, breast cancer, glioma, small cell lung cancer and pancreatic cancer." (PMID 28418922, 2017). "In breast cancer tissues with reduced cystine abundance, a negative correlation between KCTD10 and SLC7A11 and a positive correlation between USP18 and SLC7A11 were observed, respectively." (PMID 38959043, 2024). "In 2011, before the concept of ferroptosis was raised, SLC7A11 was reported to be downregulated by microRNA-26b, inducing apoptosis in MCF7 and HCC1937 but not MDA-MB-231 breast cancer cells." (PMID 33292585, 2020). "Also, in TNBC and luminal breast cancer subtypes, but not in those with positive HER2 expression, the adjacent expression of SLC7A1 and SLC7A11 is observed." (PMID 39852119, 2024). "In addition, the possible ferroptosis mechanisms of CDKN2A, PSAT1, SLC7A11, LAMP2, CAV1, and HMGB1 in TNBC and ASNS, ZFP69B, ELAVL1, TF, HELLS, and DPP4 in breast cancer have not been reported." (PMID 36568247, 2022). "Moreover, SLC7A11 was reported to be related to PI3K/AKT/mTOR signaling pathway in cancers, such as gastric cancer, glioma, pancreatic carcinoma, neuroendocrine tumors, but the interaction has not been clarified in breast cancer." (PMID 39868374, 2024).
lung cancer (167 papers, 2016 to 2026). A malignant neoplasm involving the lung. "This highlights a promising context to further investigate the use of this molecule, particularly in lung cancer in which we observed high SLC7A11 expression significantly associates with worse overall survival." (PMID 40784667, 2025). "Studies have shown that high expression of SLC7A11 is closely associated with the proliferation and survival of lung cancer cells, while the expression of GPX4 is linked to chemo resistance." (PMID 39917300, 2025). "Recently, pyruvate metabolism has been associated with GSH metabolism and ferroptosis in lung cancer cells through the plasma membrane cysteine transporter SLC7A11 (ranked 3rd by GSH metabolic process GO term annotation probability in RF classifiers)." (PMID 39934670, 2025). "Mutation of the SOX2 binding site in the SLC7A11 promoter enhances cancer cell sensitivity to ferroptosis, proposing SLC7A11 as a potential therapeutic target for lung cancer treatment." (PMID 39944353, 2024). "The β-catenin signaling pathway is crucial in lung cancer carcinogenesis, particularly regarding the downregulation of both SLC7A11 and β-catenin expression in cells associated with PRIM2 loss." (PMID 39193342, 2024). "Consistently, treatment of breast and lung cancer cells with a specific Cul-3 inhibitor (DI-1859) also caused SLC7A11 accumulation in a dose-dependent manner." (PMID 38959043, 2024). "In summary, our findings revealed that overexpression of ELF3 in the PTEN-deficient lung epithelium promoted lung cancer development by inhibiting ferroptosis partially through the directly induced expression of SLC7A11." (PMID 39695109, 2024). "ELF3 and SLC7A11 expression levels were negatively associated with lung cancer patients’ survival rates." (PMID 39695109, 2024). "In conclusion, the inhibition of ferroptosis caused by SLC7A11 up-regulation is very unfavorable for the treatment of lung cancer, but it also reflects its important regulatory role in the ferroptosis of lung cancer." (PMID 37005430, 2023). "However, mutations within the SOX2 gene lead to a downregulation of SLC7A11 expression, hence increasing the vulnerability of lung cancer cells to ferroptosis." (PMID 39875356, 2025). "Targeting SLC7A11 on MDSCs could be a promising therapeutic strategy for A. fumigatus-associated lung cancer." (PMID 41249582, 2025). "Intriguingly, KEAP1-mutant or KEAP1-deficient lung cancer cells exhibit an increased reliance on glucose, and under glucose-deprived conditions, they accumulate disulfide molecules aberrantly due to upregulated SLC7A11-mediated cystine uptake." (PMID 38428031, 2024). "Thus, SLC7A11 up-regulation can be a potential biomarker of survival in HPV/tobacco-smoke-associated lung cancer." (PMID 39769017, 2024). "The exact mechanisms underlying the increased SLC7A11 gene expression in HPV-negative or tobacco-associated lung carcinomas are unknown." (PMID 39769017, 2024). "In addition, Kirsten Rat Sarcoma (KRAS)-mutant lung cancer tumor progression is closely associated with SLC7A11 expression." (PMID 36105219, 2022). "Additionally, SLC7A11 is positively regulated in tobacco-smoke-associated lung cancer." (PMID 39769017, 2024). "On the one hand, Huaier significantly reduces the antioxidant capacity of lung cancer cells by downregulating the SLC7A11/GPX4 pathway, thereby increasing their sensitivity to ferroptosis." (PMID 40623982, 2025). "In lung cancer, the expression profiles of GPX4 (glutathione peroxidase 4) and SLC7A11 (solute carrier family 7 member 11) are closely associated with patient prognosis." (PMID 39917300, 2025).
lung cancer (continued). "Prior investigations into ferroptosis in lung cancer have largely focused on regulators like GPX4 or SLC7A11; in contrast, our work captures a broader ferroptosis-linked transcriptomic signature with direct prognostic implications." (PMID 41007424, 2025). "The reason for this stems from the differences in both response to FTIs and differences in ferroptosis defense systems where STK11/KEAP1-mutant lung cancer harbors very effective anti-ferroptosis systems through SLC7A11/GPX4, AIFM2, and AKR1C." (PMID 39995872, 2025). "We described before that LDHB is required for plasma membrane-localized SLC7A11-mediated glutathione metabolism in the tested KRAS-mutant lung cancer cells." (PMID 40090955, 2025). "Based on metabolomics data previously generated for the CCLE CLs,68 SLC7A11 correlates with glutathione levels in lung cancer CLs." (PMID 39995872, 2025). "For instance, while EGCG (epigallocatechin gallate) alleviated obesity-driven lung cancer via STAT1/SLC7A11 signaling, its low bioavailability necessitates further optimization for therapeutic use." (PMID 41368309, 2025). "The expression levels of GPX4 and SLC7A11 are significantly upregulated in lung cancer cells, and this upregulation correlates with the malignancy and prognosis of the tumor, making them potential therapeutic targets." (PMID 39917300, 2025). "We show that expression of one of these enzymes—the glutamate‐cystine antiporter SLC7A11, up‐regulated 6‐fold in a cisplatin‐resistant lung cancer cell line—has potential prognostic significance in lung cancer but not ovarian cancer." (PMID 40784667, 2025). "SLC7A11 is overexpressed in a variety of malignant tumors, such as breast, ovarian, hepatocellular, and lung cancer." (PMID 41228362, 2025). "Previous studies demonstrated that the RBP RBMS1 binds to SLC7A11 mRNA to enhance its translation, contributing to ferroptosis resistance in lung cancer." (PMID 40695795, 2025). "In summary, our study underscores the significance of SLC7A11 as a therapeutic target in non‐small cell lung cancer." (PMID 41030277, 2025). "Particularly in lung cancer, the protein RBMS1 has been implicated in radioresistance by modulating the expression of SLC7A11." (PMID 38515565, 2024). "An illustrative example of such cancer types is KEAP1-mutant lung cancer, in which KEAP1 loss-of-function mutation leads to stabilized NRF2, which in turn enhances the transcription of SLC7A11 and results in its high expression." (PMID 38428031, 2024). "On the contrary, other research has indicated that the interaction between aldo-keto reductase family 1 member B1 (AKR1B1) and STAT3 results in the upregulation of SLC7A11, which promotes ferroptosis resistance in lung cancer." (PMID 38485916, 2024). "This study revealed that SLC7A11, a cystine transporter is overexpressed in lung cancer stem-like cells." (PMID 38705513, 2024). "Butyrate can enhance ferroptosis induced by erastin in LC cells by upregulating ATF3 expression to reduce the expression level of SLC7A11, thereby inhibiting the growth of lung cancer cells." (PMID 39346734, 2024). "NaB had the opposite effect in VPA, decreasing SLC7A11 levels in other cell lines, such as osteosarcoma, lung cancer, colorectal adenocarcinoma, endometrial cancer." (PMID 38635661, 2024). "This study suggests that SLC7A11 overexpression is associated with both HPV infection and smoking, with this up-regulation linked to poor survival rates in lung cancer patients." (PMID 39769017, 2024). "For instance, manoalide and trabectedin have been shown to induce Fe2+ overload by modulating the Nrf2/SLC7A11 axis, thereby triggering ferroptosis in lung cancer cells." (PMID 39557840, 2024).
lung cancer (continued). "Further consequences of SLC7A11 overexpression entail resistance to geldanamycin in lung cancer, temozolomide in glioblastoma, and gemcitabine in pancreatic cancer." (PMID 38739940, 2024). "The ablation of RBMS1 inhibits the translation of SLC7A11, reduces SLC7A11-mediated cysteine uptake, and promotes ferroptosis in lung cancer cells." (PMID 39744129, 2024). "In lung cancer, overactivation of ATF4 is positively linked with ferroptosis resistance, due to SLC7A11 regulation by this transcription factor." (PMID 39104501, 2024). "A study investigated the role of RBMS1 in regulating ferroptosis in lung cancer through translational control of SLC7A11." (PMID 38383297, 2024). "Of note, these pathways are commonly activated in lung cancer, which in turn can lead to increased SLC7A11 expression through diverse mechanisms, including transcriptional activation or increased mRNA stability." (PMID 39769017, 2024). "Compared with normal cells, lung cancer cells A549 had higher levels of SLC7A11 expression and lower levels of PD-L1 expression, and the difference was statistically significant." (PMID 38655266, 2024). "The tumor growth inhibitory function of natural SLC7A11 inhibitors in lung cancer has been observed in vivo as well, making them as possible candidate for future studies in clinical settings." (PMID 39104501, 2024). "SOX2, a stem cell factor, has been shown to promote resistance to ferroptosis in lung cancer cells by upregulating SLC7A11, which can enhance the self‐renewal ability of these cells." (PMID 39660409, 2024). "Lung cancers with mutations in KEAP1 (an important tumor suppressor gene) are known to be radiotherapy-resistant, which highlights the key role of SLC7A11 in radioresistance." (PMID 39029955, 2024). "RBMS1 has been found to promote the progression of lung cancer by inhibiting ferroptosis through upregulating the expression of SLC7A11." (PMID 39660409, 2024). "LncRNA Uc.339 reduces the level of miR-339 by competing with pri-miR-339, alleviating the inhibitory effect on SLC7A11, and promoting the metastasis of lung cancer cells." (PMID 38515565, 2024). "Our findings suggest a complex interplay between HPV, tobacco smoking, and SLC7A11 gene expression in the development and progression of lung cancer." (PMID 39769017, 2024). "Dihydroartemisinin downregulate the level of PRIM2/SLC7A11 axis so that induce ferroptosis and inhibits the proliferation of lung cancer cell." (PMID 38738174, 2024). "Further mechanistic exploration revealed that lung cancer stem-like cells (CSLCs) resist ferroptosis by upregulating the cystine transporter SLC7A11, activated by the stem cell transcription factor SOX2." (PMID 39944353, 2024). "Sulforaphane demonstrates ferroptosis-mediated antiproliferation of lung cancer cells by downregulating the ferroptosis-inhibiting SLC7A11 gene." (PMID 38892270, 2024). "SLC7A11, which is highly expressed in lung cancer patients, triggers the ferroptosis of lung cancer cells by downregulating miR-27a-3p, suggesting that miR-27a-3p inhibits ferroptosis." (PMID 39759512, 2024). "outlines ferroptosis-related biomarkers in lung cancer, where markers like ACSL3, FANCD2, and SLC7A11 are associated with adverse prognosis and abbreviated overall survival." (PMID 38515565, 2024). "Mutations or defects in KEAP1 in lung cancer cells result in constitutive activation of NRF2 and aberrant expression of NRF2 transcriptional targets, including SLC7A11." (PMID 39029955, 2024). "Curcumin and quercetin inhibited the expression of circFOXP1 in lung cancer cells by regulating the miR-520a-5p/SLC7A11 axis, which in turn affected cell growth, migration and invasion as well as ferroptosis." (PMID 39309443, 2024). "Emerging studies have shown that YTHDC2 expression was low in lung cancer and that it induced ferroptosis by inhibiting the expression of SLC7A11 through m6A modification." (PMID 38392340, 2024).
lung cancer (continued). "By integrating the clinical analyses and genetic mouse models, we found that ELF3 overexpression in the PTEN-deficient background promoted cell proliferation and inhibited ferroptosis by inducing SLC7A11 expression, thus promoting lung cancer development." (PMID 39695109, 2024). "To determine the effect of tobacco smoking on SLC7A11 gene expression in lung cancer, we used the UCSC Xena program with information from the GDC TCGA Lung Cancer Database." (PMID 39769017, 2024). "Both smoking and HPV infection are known to contribute to lung cancer development and they can potentially influence the expression and activity of SLC7A11, making it a relevant target for this specific patient population." (PMID 39769017, 2024). "We found that solute carrier family 7 member 11 (SLC7A11/xCT), an antiporter that mediates the uptake of extracellular cystine, is frequently enhanced at transcript levels in HPV-associated lung carcinomas." (PMID 39769017, 2024). "More studies are warranted to dissect the role and mechanisms involved in SLC7A11 overexpression in HPV-positive and tobacco-smoke-associated lung carcinomas." (PMID 39769017, 2024). "In this sub-cohort, we found that SLC7A11 was more frequently detected in HPV-positive lung carcinomas when compared to HPV-negative cases (p = 0.0080)." (PMID 39769017, 2024). "We found that HPV is present in 4% of lung carcinomas and that the SLC7A11/xCT gene is frequently up-regulated in HPV-positive lung carcinomas." (PMID 39769017, 2024). "We have demonstrated a significantly higher prevalence of SLC7A11 overexpression in HPV16-positive lung carcinomas compared to HPV16-negative tumors, particularly in patients with a history of heavy smoking." (PMID 39769017, 2024). "SLC7A11 is indeed a promising anticancer target for drug development against Smoker+/HPV+/SLC7A11+ lung carcinomas." (PMID 39769017, 2024). "Further studies showed that circ FOXP1 can increase the expression of SLC7A11 by directly sponging miR-520a-5p in lung cancer cells to promote lung cancer tumor growth." (PMID 37005430, 2023). "DHA can down-regulate PRIM2 and regulate the expression of SLC7A11 and β-catenin, thereby inhibiting the proliferation and cloning ability of lung cancer cells and promoting ferroptosis." (PMID 37005430, 2023). "Lung cancer stem-like cells exhibited higher SLC7A11 expression that did lung cancer cells, and the stem cell transcription factor SOX2 activated SLC7A11, thus enhancing the resistance of lung cancer stem-like cells to ferroptosis." (PMID 37433225, 2023). "Further studies showed that SLC7A11 regulated ferroptosis in lung cancer mainly by regulating metabolic demand." (PMID 37005430, 2023). "Studies have shown that SENP1 can modulate the inflammatory signal A20, which interacts with ACSL4 and SLC7A11 to regulate ferroptosis in lung cancer cells." (PMID 36639654, 2023). "Meanwhile, the chaperone protein containing TCP1 subunit 3 (CCT3) can also inhibit ferroptosis by promoting SLC7A11 expression in lung cancer cells." (PMID 37005430, 2023). "And the histone deacetylase inhibitor vorinostat was reported to increase the sensitivity to EGFR-TKIs by inducing ferroptosis through reducing the expression of SLC7A11 (xCT) in lung cancer cells." (PMID 36926345, 2023). "In lung cancers, a high level of intracellular glutamate is correlated with the expression of the cystine/glutamate antiporter (xCT/SLC7A11)." (PMID 36817470, 2023). "Elevated levels of leptin can potentially accelerate the progression of obesity-related lung cancer through the activation of the STAT1- solute carrier family 7 member 11 (SLC7A11) pathway, which mediates ferroptosis." (PMID 37943609, 2023). "Although we found that HO-3867 did not affect the expression of SLC7A11, curcumin is known to modulate the levels of SLC7A11 in lung cancer and lung epithelial cells." (PMID 36814470, 2023).